TRIP13 (thyroid hormone receptor interactor 13)
Diseases named in the same sentence as TRIP13 in open-access papers (continued):
Sharing a sentence is not in itself a finding about the gene and the disease.
cancer (continued). "TRIP13 (Thyroid receptor-interacting protein 13) has a role in cell cycle arrest and cancer progression." (PMID 36371386, 2022). "For all three cancer types, TRIP13 mainly located in the nucleus was identified as a common leader gene." (PMID 36226184, 2022). "Research revealed that the abnormal expression of TRIP13 indicated a poor prognosis of cancer patients." (PMID 35601150, 2022). "There is mounting evidence that TRIP13 protein levels are overexpressed in several human cancers, including ovarian cancer, colorectal cancer, prostate cancer and Wilms' tumour." (PMID 35322916, 2022). "Although it plays an important role in meiotic regulation, excessive expression or amplification of TRIP13 has been found in more than one human cancer." (PMID 33237662, 2021). "For mice injected with HT29p53‐mut,MSS cells, there were, after 8 and 21 days of culture, reduced numbers of cancer cells in cultures from bone marrow of mice injected with TRIP13 knockdown cells as compared to cells transfected with NT shRNA." (PMID 33037736, 2020). "The results showed marked bone colonization by cancer cells transfected with NT shRNA as compared to cells transfected with TRIP13 shRNA." (PMID 33037736, 2020). "Thyroid hormone receptor interactor 13 (TRIP13) is a cancer predisposition gene encoding highly conserved AAA‐ATPase family members, and TRIP13 mutations confer CIN and premature chromosome segregation dysfunctions, leading to aneuploidy." (PMID 33037736, 2020). "Although TRIP13 is highly expressed in many human cancers, the biological molecular mechanism is largely unclear." (PMID 31740732, 2019). "In recent years, the role of AAA ATPase TRIP13 in the occurrence and development progress of malignant tumors has received significant attention." (PMID 31533816, 2019). "Conversely, several studies have highlighted that TRIP13 is overexpressed in many cancer types, and that high-level TRIP13 expression correlates with poor patient outcomes." (PMID 30341343, 2018). "Among the genes, TRIP13 draw our great interests as a high TRIP13 expression pointed to a poor prognosis of patients with various cancers including HCC." (PMID 30564064, 2018). "The proposed dual roles of TRIP13 in the mitotic checkpoint mirror a similar duality in its observed roles in cancer." (PMID 30341343, 2018). "Grandori and colleagues reported that TRIP13 is a c-MYC dependent synthetic lethal gene in c-MYC over-expressed cancer cells." (PMID 28424416, 2017). "TRIP13 knockdown can delay metaphase-to-anaphase transition, while TRIP13 overexpression can trigger premature mitotic checkpoint silencing and thereby promote cancer development." (PMID 28056099, 2017). "KIFC1 was overexpressed in 42 out of 459 analyses (cancer tissue versus normal tissue) and TRIP13 in 69 out of 467 analyses (fold change threshold: 2; p value threshold: 1 × 10−4)." (PMID 26527623, 2016). "Intriguingly, human TRIP13 has also been identified as an oncogene: TRIP13 is overexpressed in a number of human cancers, and can promote proliferation and invasion when overexpressed in human cell lines." (PMID 25918846, 2015). "Finally, given the additional association of human TRIP13 with a number of cancer types, addressing the fundamental mechanistic questions regarding how this enzyme recognizes and remodels its substrates will be important for understanding TRIP13's multiple roles in human health and disease." (PMID 25918846, 2015). "In our pan-cancer analysis, TRIP13 was significantly upregulated in multiple tumors." (PMID 41007830, 2025). "Therefore, the DNA methylation levels of TRIP13 in human cancer were investigated using the GCSA database." (PMID 40441196, 2025). "Prior studies indicate a close link between TRIP13 and immune responses in cancers." (PMID 41007830, 2025).
cancer (continued). "In the current study, we conducted a pan-cancer analysis of TRIP13 using data available online." (PMID 40441196, 2025). "In addition, the xCell database was used to analyze the relationship between TRIP13 expression and the stromal score, immunological score, and microenvironment score for these 43 types of cancer." (PMID 40441196, 2025). "Cancer cells overexpressing Mad2 have an increased dependency on TRIP13 for their mitotic exit." (PMID 40228580, 2025). "Notably, several cancer-associated genes are located within a 1 Mb proximity including CLPTM1L, TERT, BRD9, TRIP13, NKD2, LPCAT1, and IRX4." (PMID 40278994, 2025). "Hence, we examined the relationship between TRIP13 expression and immune cell infiltration in 43 forms of cancer using the TIMER2.0 database and the xCell database." (PMID 40441196, 2025). "TRIP13 is overexpressed in these cancers, which correlates with poor clinical outcomes." (PMID 40228580, 2025). "Moreover, this study investigated the correlation between TRIP13 methylation levels and cancer prognosis." (PMID 40441196, 2025). "In addition, we discovered that TRIP13 participated in the cell cycle during Gene Ontology and Kyoto Encyclopedia of Genes and Genomes enrichment analysis for most cancers." (PMID 40441196, 2025). "As documented in prior studies, TRIP13 expression is a significant factor in various human cancers." (PMID 41007830, 2025). "Collectively, our findings suggest that TRIP13 may act as a potential prognostic marker and novel target for cancer therapy." (PMID 40441196, 2025). "TRIP13 is upregulated across diverse oncological categories, such as colorectal, lung, head and neck, breast, liver, and prostate cancers." (PMID 41007830, 2025). "As such, TRIP13 overexpression leads to the activation of HORMA domain proteins to induce chromosomal instability and is associated with a poor prognosis in several types of cancer." (PMID 38216586, 2024). "The dual role of TRIP13 in mitotic checkpoints reflects the similar duality observed in cancer." (PMID 39187490, 2024). "Reinforcing this hypothesis, similar conclusions have been drawn from research conducted on various solid tumors, where the influence of TRIP13 on cancer progression has been similarly observed." (PMID 38464090, 2024). "Stronger immunostaining of the TRIP13 protein was observed in cancer than in normal lung tissues." (PMID 38067275, 2023). "Since TRIP13 overexpression is involved in drug resistance in various cancer cells, TRIP13 might be a potential target molecule for cancer therapy." (PMID 38067275, 2023). "To validate differential expression of TRIP13, in important GI cancers (COAD, ESCA, GBM, LIHC, PAAD, and STAD), box plot analysis was performed, where we have noticed that PAAD and LIHC were only cancer conditions, that showed remarkably higher TRIP13 expression." (PMID 38074464, 2023). "Notably, TRIP13 has been shown to be overexpressed in several types of cancers, and its aberrant expression is involved in the malignant transformation of various types of cancer cells, including BrCa cells." (PMID 37627217, 2023). "The oncogenic role of TRIP13 has been established in the development of other cancers." (PMID 37432513, 2023). "However, further studies are required to elucidate the mechanism of TRIP13-induced cancer progression." (PMID 38012658, 2023). "TRIP13 is frequently upregulated in many cancers, including CRCs." (PMID 35194944, 2022). "Our findings provided mechanistic insights relevant for the exploitation of future Trip13 inhibitors for cancer therapy by defining Plin2 as predictive marker for the susceptibility of tumors to a respective targeted therapy in the context of a precision medicine approach." (PMID 36031387, 2022).
cancer (continued). "TRIP13 regulates spindle assembly checkpoint and DNA repair pathways by promoting non‐homologous end joining, which accounts for the chromosomal instability in most human cancers." (PMID 35194944, 2022). "It shows a potential oncogenic role of TRIP13 in cancer development." (PMID 33237662, 2021). "Previous reports demonstrated that TRIP13 may directly regulate cell cycle progression, tumorigenesis, invasion and chemoresistance in other cancer types." (PMID 34066132, 2021). "Previous researches reported that TRIP13 exerted a cancerogenic role in a series of cancer." (PMID 32694945, 2020). "TRIP13 is highly expressed in several cancers and is closely connected with cancer progression." (PMID 30564064, 2018). "TRIP13 is identified as an oncogene, whose overexpression can lead to many human cancers." (PMID 30564064, 2018). "Some of these genes, such as TRIP13, PYY, are known to be cancer-associated." (PMID 29378509, 2018). "The contributions of TRIP13 to tumorigenesis and cancer progression remain largely mysterious." (PMID 30341343, 2018). "Most recently, relationship between TRIP13 and human cancer attract scientist's attention." (PMID 28424416, 2017). "Generally, TRIP13 is required for chromosome structure and recombination during mitosis, and is also a mitotic checkpoint-silencing protein, suggesting its regulatory effects on checkpoint proteins and its potential role in promoting cancers." (PMID 28157697, 2017). "It is interesting that TRIP13 (by its interaction with CMT2) is implicated in cancer progression as spindle checkpoint defects are known to contribute to loss of chromosome integrity, which can lead to aneuploidy, a common feature of cancer cells." (PMID 22075945, 2012). "Although TRIP13 has been linked to several cancers, its role in OC is not clearly defined." (PMID 41907269, 2026). "Meanwhile, overexpression of Trip13 may promote the development of cancer." (PMID 37942576, 2023). "However, the described functional link of Trip13‐lipid metabolism and especially Plin2 in the regulation of mitosis, provides novel implications for cell biology as well as for the development of antimitotic treatment strategies against cancer." (PMID 36031387, 2022). "Therefore, abnormal expression of TRIP13 is a common occurrence in cancer cells." (PMID 33237662, 2021). "Here we find that melatonin (MT) not only downregulates TRIP13 but also the DNA repair proteins RAD51 and XRCC5, thereby inhibiting aberrant DNA repair in cancer cells." (PMID 41145438, 2025). "Among the genes closely related to SPSB2 expression, CDC45, RAD51, TRIP13, MYBL2, and CDC20 play essential roles in cancer development." (PMID 40149497, 2025). "Thyroid hormone receptor interactor 13 (TRIP13) plays a critical role in mitosis and has emerged as a potential target for cancer therapy." (PMID 40228580, 2025). "TRIP13 expression and MDSC invasion were significantly correlated in all 40 malignancies or cancer subtypes in the TIMER2.0 database, except for THCA and UCS." (PMID 40441196, 2025). "We found that TRIP13 was negatively correlated with poor immune infiltration, especially with CD4 and CD8, in most types of cancers." (PMID 40441196, 2025). "In particular, we noted that cancer-related genes including METTL1, ALKBH2, PSPH, PTPRC, and TRIP13 contributed the most to the identification, which indicated the great biological interpretability of our model." (PMID 38243719, 2024). "We measured the effect of inhibiting TRIP13 on cell survival and found that the addition of 10 μM DCZ0415 to the growth media reduced the cancer cell surviving fraction in all cell lines by an average of 64% (CI95% 55–73%)." (PMID 38216586, 2024). "We found that in the case of the ALT high TEL high phenotype, genes TRIP13, TPX2, and MCM7 were upregulated in eight cancer types and ADAMTS8 in seven cancer types was downregulated." (PMID 38763334, 2024).
cancer (continued). "We focused on thyroid hormone receptor interactor 13 (TRIP13) and investigated its cancer-promoting functions in LUAD cells." (PMID 38067275, 2023). "Thyroid hormone receptor interactor 13 (TRIP13), an AAA-ATPase, participates in the development of many cancers." (PMID 35517402, 2022). "Since, in CRCs, FGFR4 mediates cancer progression via phosphorylation of STAT3, we assessed its phosphorylation status at the Y705 site in CRC cells after TRIP13 shRNA knockdown and treatment with DCZ0415." (PMID 35194944, 2022). "Thyroid hormone receptor interactor 13 (TRIP13) plays a crucial role in poor prognosis and chemotherapy resistance of cancer patients." (PMID 35601150, 2022). "Previous studies have reported that TRIP13 is a novel component of the SAC pathway and demonstrated to be the top-ranked genes related to chromosome instability (CIN) in several cancers." (PMID 34066132, 2021). "In this study, by reanalyzing AAA ATPase gene expression profiles in the The Cancer Genome Atlas Liver Hepatocellular Carcinoma (TCGA-LIHC) data collection, we first identified TRIP13 was the most significant differential expressed gene." (PMID 31533816, 2019). "We demonstrated that the combination of Aurora kinase A inhibition and TRIP13 depletion causes extensive apoptosis selectively in retinoblastoma (RB1, Rb) deficient cancer cells, sparing Rb-proficient and non-transformed cells." (PMID 40228580, 2025). "Despite a high RNA expression in the germline and many types of cancer, and low RNA expression in normal somatic tissues, TRIP13 is not strictly specific to cancer and the germline as it is also involved in the mitotic spindle assembly checkpoint." (PMID 38216586, 2024). "One gene strongly associated with increased IR resistance in our cells appeared to be TRIP13, and we here show that the putative TRIP13 inhibitor DCZ0415 leads to a decreased DNA damage response, which may allow for improved cancer treatment options." (PMID 38216586, 2024). "The TRIP13 gene (Case 2) is located on 5p15 and can be highly expressed in various malignant tumors, although no RMS has been reported." (PMID 36686750, 2022). "CELSR3, TRPM2, and TRIP13 are over-expressed in all the 13 cancers, TNXB is under-expressed in all the 13 cancers, KCNAB1 is over-expressed in KIRC but under-expressed in the other 12 cancers." (PMID 30729033, 2019). "BUBR1 and TRIP13, but not CEP57, have a common role in the mitotic checkpoint, which has been linked to the separation in cancer phenotypes among MVA syndrome patients." (PMID 30035751, 2018). "While anlotinib is not a specific TRIP13 inhibitor, this finding highlights the potential for repurposing existing drugs or identifying novel drug scaffolds with dual or multi-target activity against TRIP13 and other cancer-relevant targets." (PMID 40228580, 2025). "Moreover, genes that are upregulated and downregulated at both RNA and protein levels across multiple types of cancers were identified and defined as PCUGs and PCDGs, respectively, which encompass a large number of oncogenes such as MKI67, TRIP13, SMC4, UBE2C, CDK1, and TOP2A." (PMID 39884577, 2025). "TRIP13 protein was highly expressed in cancer lesions but weakly expressed in noncancerous areas." (PMID 37627217, 2023). "Whereas in other cancers (COAD, ESCA, GBM, and STAD) there was no encouraging expression pattern of TRIP13 as compared to their respective normal tissues." (PMID 38074464, 2023).
genetic disorder (2 papers, 2020 to 2021). "Mosaic variegated aneuploidy (MVA) is a rare genetic disorder caused by mutations in BUB1B, CEP57, or TRIP13." (PMID 32884756, 2020).
adenocarcinoma (1 paper, 2019). A common cancer characterized by the presence of malignant glandular cells. "Among them, the mRNA expression of 5 genes, namely, BIRC5, MCM4, CDC20, KIAA0101, and TRIP13, were significantly upregulated among TN adenocarcinomas (all P < 0.05)." (PMID 31093306, 2019).
TRIP13 also shares sentences with these, for which no sentence is quoted: non-small cell lung carcinoma (3 papers); colon cancer (2); eosinophilic leukemia (2); myeloid leukemia (2); ovarian cancer (2); paraganglioma (2); perihilar cholangiocarcinoma (2); pheochromocytoma (2); triple-negative breast carcinoma (2); allergies (1); Alzheimer disease (1); autoimmune disease (1); Azoospermia (1); bacterial infection (1); chronic kidney disease (1); cognitive delay (1); colorectal adenocarcinoma (1); COVID-19 (1); cutaneous squamous cell carcinoma (1); cutaneous T-cell lymphoma (1); diffuse large B-cell lymphoma (1); ductal carcinoma in situ (1); esophagus cancer (1); gastric adenocarcinoma (1); gastrointestinal tumours (1); gynecologic cancer (1); infection (1); invasive ductal carcinoma (1); invasive lobular carcinoma (1); malignant fibrous histiocytoma (1).
A further 18 diseases each share a sentence with TRIP13 in 1 paper.